RAB9A (RAB9A, member RAS oncogene family)
Description:
The small GTPases Rab are key regulators of intracellular membrane trafficking, from the formation of transport vesicles to their fusion with membranes. Rabs cycle between an inactive GDP-bound form and an active GTP-bound form that is able to recruit to membranes different sets of downstream effectors directly responsible for vesicle formation, movement, tethering and fusion (By similarity). RAB9A is involved in the transport of proteins between the endosomes and the trans-Golgi network (TGN). Specifically uses NDE1/NDEL1 as an effector to interact with the dynein motor complex in order to control retrograde trafficking of RAB9-associated late endosomes to the TGN. Involved in the recruitment of SGSM2 to melanosomes and is required for the proper trafficking of melanogenic enzymes TYR, TYRP1 and DCT/TYRP2 to melanosomes in melanocytes (By similarity).
Synonyms: RAB9
Tractability: Small molecule: a structure with a bound ligand is known; it belongs to a druggable protein family. Antibody: UniProt places it where antibodies can reach, with high confidence; its Gene Ontology location is reachable by antibodies, with medium confidence. PROTAC: ubiquitination databases record sites on it; its protein half-life has been measured; a small molecule that binds it is known.
Target class: Enzyme; Hydrolase
Gene: Protein-coding gene on chromosome X (13,689,122 to 13,710,504, forward strand). Ensembl gene ENSG00000123595.
Subcellular location: Cell membrane; Endoplasmic reticulum membrane; Golgi apparatus membrane; Late endosome; Cytoplasmic vesicle, phagosome membrane; Cytoplasmic vesicle, phagosome; Cytoplasmic vesicle membrane; Melanosome
Subcellular location (Human Protein Atlas): Nucleoplasm; Cytosol
Pathways (Reactome):
Vesicle-mediated transport: RAB GEFs exchange GTP for GDP on RABs; Retrograde transport at the Trans-Golgi-Network
Metabolism of proteins: RAB geranylgeranylation
Signal Transduction: RHOBTB3 ATPase cycle
Gene Ontology:
Molecular function: G protein activity; GDP binding; GTP binding; GTPase activity; protein binding; identical protein binding
Biological process: positive regulation of exocytosis; receptor-mediated endocytosis; regulation of protein localization; retrograde transport, endosome to Golgi; Rab protein signal transduction
Cellular component: cytoplasmic vesicle membrane; extracellular exosome; late endosome; lysosome; phagocytic vesicle; cytosol; melanosome; trans-Golgi network membrane; transport vesicle; endoplasmic reticulum membrane; Golgi membrane; phagocytic vesicle membrane; plasma membrane
Homologues: Orthologues: chimpanzee RAB9A (100% identical), dog RAB9A (99% identical), macaque RAB9A (99% identical), guinea pig RAB9A (99% identical), pig RAB9A (99% identical), rat Rab9a (96% identical), mouse Rab9 (96% identical), tropical clawed frog rab9a (90% identical), zebrafish rab9a (85% identical). Paralogues in human: RAB9B (76% identical), RAB7A (51% identical), RAB7B (40% identical), RAB37 (37% identical), RAB11A (37% identical), RAB11B (37% identical), RAB26 (37% identical), RAB21 (36% identical), RAB27A (36% identical), RAB8B (36% identical), RAB35 (36% identical), RAB5B (36% identical), and 56 more.